SST (somatostatin)
Diseases named in the same sentence as SST in open-access papers (continued):
Sharing a sentence is not in itself a finding about the gene and the disease.
cancer (88 papers, 2002 to 2026). A tumor composed of atypical neoplastic, often pleomorphic cells that invade other tissues. "It is known that somatostatin is linked with such effects in humans, and somatostatin and its analogues have already been explored as targets for anti-cancer therapies." (PMID 39194685, 2024). "Understanding the role of the SRIF system in CRC may help to identify new diagnostic and therapeutic targets with new forms of SST analogs (SSAs) in this cancer." (PMID 39518025, 2024). "Serum methylated SST was significantly associated with cancer-specific survival among all other detected markers tested in the same study (TAC1, MAL, SEPT9, NELL1, CRABP1, EYA4, and CEA) at the preoperative time point, while its methylation status after operation had no value on prognosis." (PMID 30944663, 2019). "Furthermore, for the key germline/somatic mutation, environmental factors; physiological abnormalities; and changes at the morphological, biochemical and molecular levels for the cancer of different origin are also associated with changes in SST and somatostatin receptors (SSTRs)." (PMID 38203605, 2023). "Finally, we established diagnostic models for combined and individual GIT cancers, and the results suggested that the SST methylation might be a potential new marker significantly associated with pandigestive cancers." (PMID 35242243, 2022). "Understanding the role of SST expression with age will enable the better application of this neuropeptide in the diagnosis and treatment of diseases of old age (including cancers)." (PMID 42196227, 2026). "Reduced SST expression in CRC indicates a weakening in the antitumor effect of this neuropeptide in this cancer in vivo." (PMID 39518025, 2024). "The study of the pro-apoptotic activities of SST/SSAs in CRC in vitro resulted in the demonstration of certain mechanisms of apoptosis induction in cancer cells." (PMID 38540191, 2024). "On the other hand, two hypothalamic hormones, i.e., growth hormone-releasing hormone (GHRH) and SST, are affected by the aging process, which in turn influences numerous age-related changes (including cancer)." (PMID 38540191, 2024). "Combination therapy of somatostatin agonists and various chemotherapeutic drugs is being researched for a variety of cancers, including NETs, with some favorable results regarding response rates and progression-free survival." (PMID 39329930, 2024). "Downregulation of SSTR1 in patients with PCa whose disease is progressing while on ARSIs is consistent with the known antitumor effect of somatostatin and somatostatin analogs observed in other cancer types (e.g., gastrointestinal and pancreatic NE tumors)." (PMID 39352383, 2024). "The malignant cells with a cytoplasmic product of the SST IHC reaction were demonstrated to be focally localized, with a granular reaction pattern in the apical part of the cancer cells, or distributed throughout the cell cytoplasm." (PMID 39518025, 2024). "The existence of receptors sensitive to somatostatin and its analogs, other than the known SSTRs, can be explored in the context of therapeutic resistance exhibited by some cancers when treated with somatostatin analogs." (PMID 39329930, 2024). "The interplay with SSTRs and somatostatin levels in cancers is of interest since capsaicin itself also exhibits antitumoral effects." (PMID 39329930, 2024). "It was also shown that preoperative serum levels of methylated SST were significant prognostic factors for cancer recurrence, in addition to vascular embolism, perineural invasion and CEA level." (PMID 38540191, 2024). "The number of NCs expressing specific markers (including SST) decreases in adenomas and carcinomas compared to normal colonic crypts." (PMID 38540191, 2024). "Somatostatin receptor 2 (SSTR2), the most abundant receptor of somatostatin (SST), possesses immunoreactivity and is altered in many cancers." (PMID 35264912, 2022).
cancer (continued). "SST is a cyclic peptide hormone involved in the secretion of growth hormone, quiescence of stem cells and cancer development." (PMID 33960101, 2022). "SST is one of the cyclic tetradecapeptide hormones related to cancer growth, invasion, and metastasis." (PMID 34419055, 2021). "Due to its role, SST expression in cancer is evaluated extensively in order to find new biomarkers or to expand current therapeutic options." (PMID 33085037, 2021). "Altogether, several lines of evidence suggest that DNA methylation as well as histone modifications are involved in deregulated SST expression in various types of cancer." (PMID 33085037, 2021). "In the case of PDAC, it was shown that the methylation of SST promoter is a sensitive and promising molecular biomarker of this cancer." (PMID 34829972, 2021). "Instead, it is likely that SST hypermethylation has the potential as a blood‐based pan‐cancer biomarker for a broad range of tumors for initial screening in order to stratify individuals into high‐risk and low‐risk groups." (PMID 32243066, 2020). "The binding affinity of SST analogs and cytotoxic SST analog AN-162 to membrane receptors of human pediatric cancer cells (HL and RMS) expressing SSTRs was also investigated by ligand competition assay." (PMID 33297556, 2020). "With respect to diagnostics, the AUC value of SST methylation in tissue and plasma samples were 100% and 89%, respectively, demonstrating its high potential as a biomarker for cancer diagnosis." (PMID 32243066, 2020). "The SST research shows that neuropeptide GPCRs can be used as oncotargets to detect and treat a human cancer." (PMID 30008698, 2018). "Since then, SST antagonists have become attractive agents for the diagnosis and treatment of cancer." (PMID 28804185, 2017). "It is also noteworthy that SST has demonstrated an anti-proliferative activity on certain cancer cells." (PMID 28804185, 2017). "Univariate analyses showed that serum methylation levels of MAL and SST were significantly predictive of cancer-specific death." (PMID 28187169, 2017). "Peptide analogues derived from bioactive hormones such as somatostatin or certain growth factors have great potential as angiogenesis inhibitors for cancer applications." (PMID 27734947, 2016). "Due to its varied actions, somatostatin and its analogs can potentially contribute to cancer diagnosis and treatment through multiple mechanisms." (PMID 25594044, 2014). "Octreotide is an octapeptide that mimics natural somatostatin pharmacologically and possesses potent antineoplastic activity in several human cancers." (PMID 24137418, 2013). "The present study identified that the protein level of SST in the normal group was 7.399±0.956 pg/mg, which was significantly higher than that in the cancer group (5.091±0.994 pg/mg)." (PMID 24260078, 2013). "The SST protein level in the normal group was significantly higher compared with that in the cancer group (7.399±0.956 vs. 5.091±0.994 pg/mg; P<0.01)." (PMID 24260078, 2013). "It was found that receptors for peptide hormones such as GnRH and somatostatin are more intensively expressed on cancer cells, compared to normal cells and serve as targets fore-peptide ligands to cytotoxic drugs." (PMID 24223939, 2013). "In the past decade, the somatostatin-based receptor-targeted anti-cancer therapy has emerged as a promising tool in order to improve the traditional chemotherapy." (PMID 24287991, 2013). "The methylation proportion of SST was 45.1% (23/51) in the carcinoma group and 3.9% (2/51) in the normal group." (PMID 24260078, 2013). "The positive rate of DNA methylation for SST in the carcinoma group was markedly higher than that of the normal group (23/51 vs. 2/51)." (PMID 24260078, 2013). "Cytotoxic compounds linked to analogs of hormonal peptides like LHRH, bombesin, and somatostatin can be targeted to certain tumors possessing receptors for those peptides and therefore are more selective for killing cancer cells." (PMID 23316341, 2012).
cancer (continued). "Apart from the use of peptide-based LHRH agonists and antagonists for treating cancer, somatostatin analogues are the only approved cancer therapeutic peptides in the market." (PMID 23316341, 2012). "A negative influence on cell proliferation is a common characteristicof SST, which has been demonstrated e.g. in different carcinoma cell lines, but hasnever been shown for keratinocytes." (PMID 21589940, 2011). "Four genes are hypermethylated in all 9 tested cancers, while for SST (7 of 9 carcinomas), HTRA3 (1 of 9 carcinomas) and NPTX1 (5 of 10 carcinomas) a fraction of the tested carcinomas is hypermethylated." (PMID 19025626, 2008). "Examples include the study of molecular aberrations of the SST gene for multiple GI cancers, the difference in HSP90α protein across 9 different tumors, or the identification of CpG markers to detect 27 cancer types." (PMID 38539525, 2024). "There are direct and indirect antitumor effects of SST and SSAs in various cancers." (PMID 38540191, 2024). "The authors suggest that SST5 may play an important role in intestinal barrier dysfunction (induced by LPS) and mediate the beneficial effect of SST on TJ damage in cancer cells." (PMID 38540191, 2024). "Despite this, SST analogs have shown substantial potential to be combined with other therapeutic or imaging agents via bioconjugation for the targeted delivery of its payloads to SSTR-positive cancer cells." (PMID 38791582, 2024). "It was confirmed that SST methylation in pre-operative sera may even be an independent prognostic marker for assessing the risk of CRC and cancer-specific death and recurrence." (PMID 38540191, 2024). "However, another aspect we should consider here is that somatostatin and its analogues are evaluated as anticancer agents and this can have implications in the case of viral-induced cancers." (PMID 37836381, 2023). "Hence, we introduced a vaccinia virus delivery system, which expresses somatostatin fusion protein for cancer therapy, and vaccinia virus itself also has an oncolytic effect." (PMID 36207478, 2022). "Subsequently, we validated the most potent markers (ASCL1, LHX8, SST, WDR17, ZIC1 and ZNF582) in a large independent series, confirmed the accuracy (AUC = 0.89) and showed that high methylation levels are associated with progression towards cancer." (PMID 33580586, 2021). "Limited information is available about the epigenetic regulation of SST in other types of cancer." (PMID 33085037, 2021). "Therefore, we explored the SST gene methylation and expression in other cancer entities available in the TCGA database." (PMID 32243066, 2020). "The high binding affinity of the synthetic octapeptide analogs to SSTR in malignant pediatric samples suggests that children with SSTR-positive cancers might be good candidates for therapy with SST analogs, including the targeted cytotoxic SST analog AN-162." (PMID 33297556, 2020). "In diabetic or cancer therapy, somatostatin (SST) expression plays a vital role." (PMID 31387633, 2019). "We found predominant and dense interaction networks of genes engaged in neural differentiation, including the well-characterized neuroendocrine regulator somatostatin (SST) and its receptor, as well as CXCR4 and CXCR7, two chemokine receptors well-implicated in cancer metastasis." (PMID 31882655, 2019). "Previous studies have indicated that interferon and somatostatin, as well as its analogs, may be used in the treatment of carcinomas." (PMID 24944650, 2014). "Several studies have confirmed that SST and its analogs may be able to inhibit the growth of cancers." (PMID 24260078, 2013). "In addition, SST analogues cause a potent reduction in circulating levels of growth hormone (GH) and its mediator hormone IGF-1, a potent mitogen in breast and other cancers." (PMID 16018813, 2005).
cancer (continued). "However, it seems that the decrease in SST production in histologically normal colorectal tissue and CRC patients with age may indicate a putative role for SST in the pathogenesis of CRC and may be a risk factor for this cancer." (PMID 39518025, 2024). "Studies also showed that poorly differentiated CRC exhibits a lower level of SST expression; whether SST is associated with metastasis of cancer is not established yet." (PMID 38203605, 2023). "Importantly, somatostatin exerts antiproliferative and antiangiogenic effects on cancer cells." (PMID 36207478, 2022). "Therefore, somatostatin analogs (SSAs) had been studied for immunotherapy of various cancers." (PMID 35155566, 2021). "In fact, some peptide drugs (e.g., gonadotropin-releasing hormone analogs, somatostatin analogs) have been approved by the FDA to fight some cancer types (e.g., breast, prostate, lung neuroendocrine), as well as for cancer diagnosis." (PMID 40331938, 2025). "It is unclear, among others, the role of SST in CRC cell histogenesis and in increasing the population of cancer stem cells (CSCs)." (PMID 38540191, 2024). "The value indicated that the SST and SSTR mRNA expression levels in the cancer group were lower than those of the normal group." (PMID 24260078, 2013). "The expression of SST, SSTR2, SSTR3 and SSTR5 mRNA in the normal and cancer groups was detected using RT-PCR." (PMID 24260078, 2013). "In an in vitro study, they determined that somatostatin was not expressed in cancer cells, in contrast with SSTR1 which was expressed." (PMID 39329930, 2024). "FAM159B did not co-localise with NCAM1, 5-HT, or somatostatin-14/28 in any of the cancer cell lines." (PMID 36362289, 2022). "In the 65 cases of CRC, the SST expression was significantly lower in the cancer tissues than in the adjacent noncancerous tissues (0.0098 ± 0.0263 vs. 0.0819 ± 0.1372, P < 0.001)." (PMID 35242243, 2022). "In summary, our results showed that the site-specific hypermethylation of SST 1stExon increased the risks of GIT cancers and might promote tumorigenesis and cancer progression by inhibiting gene transcription." (PMID 35242243, 2022). "In the 52 cases of GC, the SST expression was significantly lower in the cancer tissues than in the adjacent noncancerous tissues (0.0086 ± 0.0176 vs. 0.0318 ± 0.0404, P < 0.001)." (PMID 35242243, 2022). "Notably, the somatostatin peptide in its native form possesses a binding affinity toward SSTR, making them an alluring targeting agent for cancer treatment." (PMID 34575511, 2021). "Findings on epigenetic mechanisms in CRC suggest that hypermethylation of SST and SSTR genes may be a critical regulator in cancer development." (PMID 34829972, 2021). "The promoter region of SST gene was found to be hypermethylated in CRC biopsies, which could be partly reversed by demethylation in cancer cell lines." (PMID 25723531, 2015). "The modified C2IIa could then be fused with polypeptides such as epidermal growth factor (EGF) or somatostatin, which promote the binding to EGF- or somatastatin-receptor that are frequently overexpressed on cancer cells." (PMID 24039769, 2013). "Herein, somatostatin (SST) and cortistatin (CORT) system [ligands and receptors (SSTR1-5)) has been classically described as the gold-standard inhibitory system for cell growth (modulating apoptosis and proliferation), which have been therapeutically evaluated and explored in several cancer types." (PMID 40268793, 2025). "Notably, the expression levels of normal pancreatic epithelial cell markers, SST and INS, were specifically higher compared to cancer cells, suggesting the normal functions of these cells, while malignant marker genes, SOX9 and KRT18, were remarkably upregulated in cancer cells." (PMID 35941362, 2022). "In case of normal aging SST mRNA expression did not alter, but decreased in cancer (p<0.05)." (PMID 25723531, 2015).
cancer (continued). "The inhibitors of epigenetic modifiers such as DNA methyl transferases and histone deacetylases also improve transcription of SSTR and somatostatin in NET and non-NET cancers." (PMID 33435224, 2021). "However, the effect of the combined treatment of SST analogs and estradiol on proliferation, epithelial mesenchyme transition (EMT) and migration of normal- and cancer-derived prostate cells has not been investigated so far." (PMID 30828298, 2019).